MUC2 (mucin 2, oligomeric mucus/gel-forming)
Diseases named in the same sentence as MUC2 in open-access papers (continued):
Sharing a sentence is not in itself a finding about the gene and the disease.
ovarian carcinoma (11 papers, 2012 to 2025). A malignant neoplasm originating from the surface ovarian epithelium. "In ovarian cancer, high MUC2 expression is associated with the polarization of TAMs toward the M2 phenotype, which supports tumor growth, metastasis, and immune suppression, in contrast to the M1 phenotype, which has anti-tumor effects." (PMID 40330466, 2025). "The observed association of MUC2 polymorphisms and endometriosis may help us further elucidate the link between endometriosis and certain subtypes of ovarian cancer, if such genetic alterations were also present in the ovarian cancer patients." (PMID 22417007, 2012). "MUC2 is a mucin glycoprotein that is aberrantly overexpressed in ovarian cancer, contributing to tumor progression by influencing immune cell behavior, particularly macrophages." (PMID 40330466, 2025). "In the Cox regression analysis, MUC2 overexpression was found to be an independent prognostic factor for ovarian cancer patients, of which the hazard ratio (HR) was 2.354 (95% confidence interval (CI): 1.031-10.707, p=0.005)." (PMID 24324582, 2013). "In conclusion, our study has demonstrated that MUC2 overexpression in ovarian cancer decreases both the progression-free survival rate and the overall survival rate of cancer patients." (PMID 24324582, 2013). "We observed that an elevated MUC2 level in ovarian cancer tissues was often accompanied by a significant upregulation of COX-2 expression in ovarian cancer cells (accompanied by an upregulation of the PGE2 concentration)." (PMID 24324582, 2013). "In addition, MUC2 overexpression in ovarian cancer has also been connected to M2 macrophage polarization and poor patient survival." (PMID 34357018, 2021). "Interestingly, MUC2 overexpression is connected with M2 macrophage polarization and poor survival in ovarian cancer patients." (PMID 34300195, 2021). "Mucin 2 (MUC2) is a mucin molecule aberrantly expressed by ovarian cancer cells." (PMID 24324582, 2013). "Therefore, future studies to identify methods of inhibiting MUC2 expression in ovarian cancer (e.g., using small interfering RNAs) would be worthwhile." (PMID 24324582, 2013). "Here, we collected 102 consecutive ovarian cancer specimens and used the multiple immuno-histo-chemical/-fluorescent technique to determine the correlations between the MUC2 expression status, the ratio of M1/M2 TAMs and the densities of cyclooxygenase-2 (COX-2)+ TAMs and COX-2+ cancer cells." (PMID 24324582, 2013). "Moreover, considering that the reduced M1/M2 ratio has the highest HR, this pathological factor might have played a major role in the adverse outcome of MUC2++/+++ ovarian cancer cases." (PMID 24324582, 2013). "In previous researches, a series of mucin molecules (MUCs) aberrantly secreted by ovarian cancer cells were identified, including MUC1, MUC2 and MUC16." (PMID 24324582, 2013). "For these purposes, in this study, we quantitatively analyzed the number, density and molecular characteristics of macrophages within ovarian cancer tissues and evaluated the relationships of the obtained TAM parameters with the level of MUC2 expression in cancer tissues." (PMID 24324582, 2013).
Salmonella Infections (11 papers, 2018 to 2025). Infections with bacteria of the genus SALMONELLA. "Our results also showed that BAs treatment significantly increased the number of GCs in the villi and crypts of the ileum, and the expression of MUC2 significantly increased, restoring the loss of GCs and mucus in broilers suffering from Salmonella infection." (PMID 39533418, 2024). "In the current experiment, dietary AC alleviated the adverse effects of chickens caused by Salmonella infection by up-regulating expression of ZO-1, claudin-1, occludin, and MUC2." (PMID 36670458, 2023). "The mucin Muc2 of the intestinal mucus layer is associated with the restriction of Salmonella infection in the mouse model." (PMID 34625643, 2021). "Previous studies showed that Salmonella infection induced intestinal barrier injury by suppressing gene expression of tight junction proteins (ZO-1, claudin-1 and occludin) and MUC2." (PMID 36670458, 2023). "In this study, muc2 production was decreased in the jejunum of chickens with Salmonella infection." (PMID 32180765, 2020). "Similar to previous results reported with dietary supplementation with Thr, supplementation in ovo in the present study resulted in greater MUC2 expression, which may have contributed to the establishing commensal microbiota and increased protection against Salmonella infection." (PMID 30599006, 2018). "Additionally, Salmonella infection-induced ileal mucosa damage was alleviated by exogenous IAA, as illustrated by the increased ileal villus height, and the increased numbers of Muc2-positive goblet cells in the ileum." (PMID 40773367, 2025).
gastric tumors (10 papers, 2013 to 2025). "In a previous study with 63% Hp positivity, Hp was significantly positively associated with the expression of the intestinal mucins MUC2 and MUC4 in gastric tumors." (PMID 37674528, 2023). "In contrast, Cdx2 is essential for intestinal epithelium differentiation to regulate the expression of Muc2 and Tff3, and it is upregulated during the progression of gastric tumors." (PMID 26839577, 2016). "SOX2, CDX2, MUC5AC and MUC2 expression were assessed in 201 gastric tumors by immunohistochemistry." (PMID 25300947, 2014). "Associated to mucins, too, is the family of trefoil factors, including the gastric tumor suppressors TFF1 and TTF2, which are co-localized with MUC5AC and MUC6, respectively; and TFF3, which is typically not secreted by gastric mucosa but, like MUC2, by goblet cells." (PMID 34227026, 2021).
lymph node metastasis (10 papers, 2012 to 2023). "The meta-analysis demonstrated that a low level of MUC2 expression was associated with lymph node metastasis in patients with CRC (RR, 1.41; 95% CI, 1.25–1.60; P < 0.00001)." (PMID 29967641, 2018). "Specifically, the MUC2 marker in common ductal adenocarcinoma has been associated with less aggressive behavior, showing an inverse relationship with the presence of vascular invasion and lymph node metastasis." (PMID 25299496, 2014). "Low levels of MUC2 expression have also been shown to correlate with lymph node metastasis." (PMID 36900282, 2023). "In conclusion, findings from the current study suggest that MUC1 and MUC2 expression levels in CRC tissues are associated with OS, DFS/RFS, tumor site, depth of invasion, lymph node metastasis, distant metastasis, tumor stage, histologic type, and lymphatic invasion." (PMID 31933627, 2019). "MUC2 and MUC6 have been related to lymph node metastasis in LUAD patients." (PMID 36059804, 2022). "None of the expression of MUC1, MUC2, and MUC4 was significantly related to gender, age, differentiation, lymph node metastasis, or depth of invasion." (PMID 23101681, 2012).
endotoxemia (9 papers, 2016 to 2022). "In mice with LPS (5 mg/kg)-induced endotoxemia, the increased translocation of gut microbial components and higher mortality caused by Mucin 2 deficient (Muc2−/−) could be significantly improved by the pre-administration of broad-spectrum antibiotic cocktail before endotoxemia." (PMID 34949194, 2021). "Moreover, LA5 improved gut permeability defect (gut leakage) and leaky gut-induced systemic inflammation as indicated by FITC-dextran assay, ZO-1tight junction protein, endotoxemia, colon mucin production (gene expression of muc2) and serum cytokines (TNF-α, IL-6, and IL-10)." (PMID 33737543, 2021).
necrotizing enterocolitis (9 papers, 2012 to 2025). Necrotizing enterocolitis (NEC) is a devastating disease that affects mostly the intestine of premature infants. "An impaired MUC2 synthesis predisposed preterm CV piglets to develop necrotizing enterocolitis, and a defect in the production of MUC2 dramatically increased the sensitivity of mice to infection with S. Typhimurium." (PMID 36768650, 2023). "In pigs, preterm conditions have been shown to impair MUC2 synthesis, predisposing young piglets to develop necrotizing enterocolitis." (PMID 24609095, 2014). "Both DRG1, which has been seen to have a protective effect on epithelial junction proteins under the conditions of necrotizing enterocolitis, and MUC2 were uniquely upregulated by HFD+OC." (PMID 39588046, 2024). "In a murine model for necrotizing enterocolitis, HMOs pooled from human milk increased the expression of mucin 2 (MUC2), thus increasing mucus production, while a reduction in the intestinal permeability was detected by dextran permeability." (PMID 35844612, 2022). "According to a previous report, milk-derived EVs could safeguard against necrotizing enterocolitis by regulating Muc2 expression." (PMID 40361597, 2025). "In addition, it has been reported that mEVs could protect necrotizing enterocolitis via modulating expression of Mucin 2 (MUC2) and abundance of MUC2+ goblet cells." (PMID 34373759, 2021). "In human intestinal inflammatory diseases such as ulcerative colitis and necrotizing enterocolitis (NEC), the synthesis of MUC2 mucin is decreased, which might lead to increased bacterial-epithelial interaction." (PMID 22723890, 2012).
enteritis (8 papers, 2016 to 2024). Inflammation of the small intestine. "It was previously reported that mice with mutations in the gene encoding MUC2 develop spontaneous enteritis and diarrhea." (PMID 34641356, 2021). "Mucin 2 (MUC2) secreted by goblet cells is the most abundant mucine in the mucous layer, and the expression of MUC2 is closely related to the occurrence of enteritis, but the specific mechanism is still unclear." (PMID 36132154, 2022). "A significant reduction in the colonic expression level of MUC2 has been observed in patients with enteritis." (PMID 33532501, 2021). "Fish fed the BG2 diet had lower blood cholesterol concentration, developed enteritis, had lower expression of muc2 in the distal intestine, and had a compromised barrier status in the intestine." (PMID 33679713, 2020). "Regardless of butyrate administration, mice with enteritis displayed a trend of decreased (P = 0.053) Muc2 expression relative to mice without enteritis." (PMID 28861518, 2017). "Administration of butyrate at concentrations of 80 and 100 mM increased Muc2 expression in mice without enteritis (P < 0.023) and demonstrated a trend for increased (P < 0.088) Muc2 expression in mice with enteritis." (PMID 28861518, 2017). "Mice with enteritis exhibited reduced expression of Muc2 as compared to mice without enteritis (P < 0.001)." (PMID 28031748, 2016).
gastric adenocarcinoma (8 papers, 2016 to 2024). "To better define their correlation, we analyzed the expression levels of KLF4 and MUC2 from TCGA stomach adenocarcinoma database." (PMID 27277677, 2016). "HNF4α expression in intestinal-type gastric adenocarcinomas correlated with the expression of MUC2." (PMID 39768557, 2024). "Immunohistochemical staining of CD10, MUC2, MUC5AC, and MUC6 was performed in 257 tissue samples from patients with early differentiated gastric adenocarcinomas." (PMID 34256780, 2021). "Immunohistochemistry revealed that the tumor cells were positive for MUC5AC, but negative for MUC2 and MUC6, leading to a final diagnosis of foveolar-type gastric adenocarcinoma." (PMID 37663228, 2023).
Infertility (8 papers, 2012 to 2025). "Polymorphisms in MUC2 have also been associated with the development of endometriosis and infertility." (PMID 40724834, 2025). "Amongst the gel-forming mucins identified in humans, MUC2, MUC5AC, MUC5B and MUC6, MUC2 related polymorphisms have been related to infertility and endometriosis." (PMID 37674657, 2023). "Recently, it has been suggested that CYP17, VDR, MUC17, COX-2, WNT4, E-cadherin, CYP19, CYP17, TYK2, NFKB1, and MUC2 gene variants also contributed to endometriosis-related infertility." (PMID 28405865, 2017). "Haplotype analysis of the endometriosis associated SNPs in MUC2 also showed significantly association between the most common haplotypes and endometriosis or endometriosis-related infertility." (PMID 22417007, 2012). "Our data revealed two MUC2 polymorphisms (rs10794288 and rs10902088) were associated with endometriosis development and the related infertility." (PMID 22417007, 2012). "MUC2 polymorphisms, especially rs10794288 and rs10902088, are associated with endometriosis as well as endometriosis-related infertility." (PMID 22417007, 2012). "Genotyping of six SNPs (rs2856111, rs11245936, rs10794288, rs10902088, rs7103978 and rs11245954) within MUC2 gene were performed by using Taqman genotyping assay; individual SNP and haplotype associations with endometriosis and endometriosis-related infertility were assessed by χ2 test." (PMID 22417007, 2012). "The results imply that MUC2 may play a role in the pathogenesis of endometriosis and endometriosis-related infertility, while the mechanisms underlying this phenomenon remain to be elucidated." (PMID 22417007, 2012). "Therefore, haplotypes of these SNPs in MUC2 gene could serve as an indicator of susceptibility to endometriosis and endometriosis-related infertility." (PMID 22417007, 2012). "Both MUC2 and MUC-4 have been shown to be crucial to successful implantation, polymorphisms of each being linked to endometriosis and infertility." (PMID 33193109, 2020). "Genetic alterations of mucin genes, such as MUC2 and MUC4, were previously identified to be associated with endometriosis and related infertility." (PMID 26285705, 2015). "Our data present MUC2 as a new candidate involved in development of endometriosis and related infertility in Taiwanese Han women." (PMID 22417007, 2012). "Interestingly, genetic polymorphisms in MUC2 and MUC4 were recently reported to be associated with endometriosis development and the related infertility." (PMID 26285705, 2015). "Since MUC2 is not as well investigated as some other mucins in reproductive organs, its molecular function in endometriosis and infertility is worth future study." (PMID 22417007, 2012).
lung carcinoma (8 papers, 2018 to 2025). "Moreover, MUC2 is associated with glycosylation in lung cancer, and its amount is associated with airway inflammation." (PMID 40655139, 2025). "The MUC2 expression landscape in lung cancer is intricate, varying significantly across tumor types and stages, though it is less frequently encountered compared to gastrointestinal malignancies." (PMID 40655139, 2025). "Among mutated genes, we noticed that MUC2 and ELAVL2 are two genes that were significantly mutated in BrM samples as compared to primary lung cancers." (PMID 39593114, 2024). "In ALK + lung cancer, there is a higher incidence of MUC1 and MUC5AC cytoplasmic expression, which, combined with a paucity of MUC2 and MUC6 expression, could lead to the biological aggressiveness of ALK + cancer." (PMID 36059804, 2022).
nematode infection (8 papers, 2009 to 2015). "In a recent study, we have shown that Muc2 mucin is an important component of innate defense in nematode infection by utilizing resistant, susceptible, and Muc2-deficient mice." (PMID 25436881, 2013). "Proliferation of intestinal goblet cells is a prominent feature of the type 2 immune response to nematode infection and both Muc2 and Muc5ac are important for worm expulsion." (PMID 26377648, 2015). "The immunohistochemical experiments performed in this study demonstrated a significant increase in expression of not only Muc5AC but also Muc2 protein in goblet cells after nematode infection." (PMID 27335862, 2013). "In contrast to clearance of nematode infection, onset of clearance of C. rodentium was preceded by an early increase in Muc1, Muc2, Muc4 and Muc13 mucin transcript levels that had returned to pre-infection levels at least four days prior to clearance." (PMID 24386378, 2013). "Shekels at al. used a mouse gut infection model to analyze the effect of nematode infection with Trichinella spiralis on mucosal muc2 and muc3 mRNA levels as well as mucus vacuole size/numbers in the small intestine." (PMID 21829463, 2011). "We investigated the role of the mucin (Muc2) in worm expulsion and host immunity in a model of nematode infection." (PMID 20138044, 2010). "Several goblet cell factors have been identified to play an important role in nematode infection including Relm-β and Muc2." (PMID 19852835, 2009). "We have previously shown that nematode infection also induced intestinal epithelial responses that were characterised by goblet cell hyperplasia and led to an increase in production of sialomucin, sulfomucin, Muc2, the resistin-like molecule beta (Retnlb), and St3gal4." (PMID 27335862, 2013). "However, this was not the case for the mice susceptible (AKR) to T muris infection, supporting the hypothesis that Muc2 contributed to host protection in nematode infection." (PMID 20138044, 2010). "TFF3 is IL-4/IL-13-regulated and interacts with the mucin MUC2 (not on array) to alter mucus viscosity, with which it co-localises in human intestinal goblet cells, and up-regulation of both these mucus components has been associated with responses to nematode infection in mice." (PMID 21682880, 2011). "Taken together, it was shown that nematode infection induces airway goblet cell hyperplasia, which is characterised by the overproduction of Muc2 and Muc5AC core peptides and of the nonmucin secretory peptide Retnlb." (PMID 27335862, 2013).
viral infection (8 papers, 2020 to 2025). "During the first 6 hours, when infectious pressure was highest, MUC2 was upregulated in viral infections." (PMID 41278481, 2025). "The upregulation of MUC2 during viral infection is expected, as cells attempt to block pathogens attachment." (PMID 41278481, 2025). "The protective role of Muc2 is mainly due to its physical properties; it forms a biopolymer matrix that binds or traps virions to block viral infection." (PMID 36102516, 2022). "Pretreatment with either drug led to altered goblet cell morphology and reduced secretion based on Muc2 staining, which significantly reduced virus infection and shedding based on qRT-PCR and ISH staining." (PMID 32350281, 2020). "MUC2, the main mucin of intestinal mucus, was higher in 3-week mucus and could play a role in blocking the viral infection in older pigs, as mucins have been shown to inhibit coronavirus infection in a glycan-dependent manner." (PMID 39304917, 2024). "Additionally, CMCTs upregulate MUC-2 and sIgA levels and modulate immune cell populations, strengthening both the intestinal chemical barrier and mucosal immunity, thereby enhancing resistance to viral infection and mitigating virus-induced intestinal damage." (PMID 40733538, 2025). "The mucus layer, primarily composed of Mucin 2(MUC2) secreted by intestinal epithelial cells, serves as the first line of defense against viral infections." (PMID 40083779, 2025). "Altered mucin structure and increased Muc2 production have been observed in intestinal viral infection, such as astrovirus, rotavirus, and transmissible gastroenteritis virus (TGEV) infections, generating widespread interest in its potential role in viral infection resistance." (PMID 36102516, 2022).
C. perfringens infection (7 papers, 2016 to 2024). "The tight junction-related genes (ZO-1, Occludin, Claudin1, and MUC2) in the jejunum down-regulated significantly (P < 0.05) in all C. perfringens infection groups compared to Control group." (PMID 35769317, 2022). "Similar with the result of MUC2 expression, the present study showed that C. perfringens infection significantly up-regulated the relative expression levels of ZO-1 and CLDN1, which was contrary to results from previous studies." (PMID 33679724, 2020). "C. perfringens infection significantly decreased the OCLN mRNA expression (P < 0.05), while L. acidophilus treatment tended to decrease MUC2 mRNA expression in the jejunum (P = 0.082)." (PMID 29599973, 2018).